LRIG3 (leucine rich repeats and immunoglobulin like domains 3)
Description:
May play a role in craniofacial and inner ear morphogenesis during embryonic development. May act within the otic vesicle epithelium to control formation of the lateral semicircular canal in the inner ear, possibly by restricting the expression of NTN1 (By similarity).
Synonyms: FLJ90440; KIAA3016
Tractability: Small molecule: it belongs to a druggable protein family. Antibody: UniProt places it where antibodies can reach, with medium confidence; UniProt predicts a signal peptide or a membrane-spanning region; its Gene Ontology location is reachable by antibodies, with medium confidence. PROTAC: ubiquitination databases record sites on it.
Gene: Protein-coding gene on chromosome 12 (58,872,037 to 58,920,551, reverse strand). Ensembl gene ENSG00000139263.
Subcellular location: Cell membrane; Cytoplasmic vesicle membrane
Subcellular location (Human Protein Atlas): Cytosol
Gene Ontology:
Molecular function: protein binding; signaling receptor activity
Biological process: sensory perception of sound; otolith morphogenesis
Cellular component: extracellular region; plasma membrane; cytoplasmic vesicle membrane
Genetic constraint (gnomAD): Loss-of-function variants: 71 observed, 107.41 expected, observed/expected ratio (o/e) 0.66, 90% interval 0.55 to 0.81. The upper end of that interval is the gene's LOEUF score, 0.81, which puts it in group 3 of 6, group 1 being the genes least tolerant of losing a copy. Missense variants: 1,202 observed, 1,350.9 expected, observed/expected ratio (o/e) 0.89, 90% interval 0.85 to 0.93. Synonymous variants: 499 observed, 509 expected, observed/expected ratio (o/e) 0.98, 90% interval 0.91 to 1.06.
Homologues: Orthologues: chimpanzee LRIG3 (99% identical), macaque LRIG3 (98% identical), dog LRIG3 (92% identical), pig LRIG3 (91% identical), guinea pig LRIG3 (91% identical), rabbit LRIG3 (89% identical), rat Lrig3 (87% identical), mouse Lrig3 (86% identical), tropical clawed frog lrig3 (68% identical), zebrafish lrig3 (46% identical), Caenorhabditis elegans sma-10 (23% identical), Drosophila melanogaster kek3 (15% identical), and 2 more. Paralogues in human: LRIG2 (52% identical), LRIG1 (48% identical), LGR6 (18% identical), LGR5 (16% identical), LGR4 (16% identical), TRIL (14% identical), CPN2 (12% identical), CHADL (12% identical), LRIT3 (12% identical), LRRC24 (11% identical), LRRTM2 (11% identical), ELFN2 (11% identical), and 10 more.
Diseases named in the same sentence as LRIG3 in open-access papers:
LRIG3 is named in the same sentence as 28 diseases in open-access papers, as found by Europe PMC text mining. Sharing a sentence is not in itself a finding about the gene and the disease. The quoted sentences say what the papers report.
glioma (8 papers, 2013 to 2026). A benign or malignant brain and spinal cord tumor that arises from glial cells (astrocytes, oligodendrocytes, ependymal cells). "In the present study, we used loss- and gain-of-function assays to show that LRIG3 significantly suppressed glioma-induced angiogenesis, both in vitro and in vivo." (PMID 33718179, 2021). "This novel LRIG3/PI3K/AKT/VEGFA axis provides new insights into the underlying mechanisms of glioma angiogenesis." (PMID 33718179, 2021). "Collectively, these results demonstrated that LRIG3 expression levels in glioma samples were negatively associated with WHO grades, and higher LRIG3 expression levels were associated with favorable prognosis in HGG patients." (PMID 31245283, 2019). "In patients with grade IV glioma, higher LRIG3 expression levels were significantly associated with prolonged post-operative overall survival (p = 0.0464)." (PMID 31245283, 2019). "Since gain-of-LRIG3 could inhibit glioma cell-induced angiogenesis, we hypothesized that loss of LRIG3 could enhance the pro-angiogenic activity of glioma cells." (PMID 33718179, 2021). "Histological analysis of intracranial xenografts and glioblastoma specimens was performed to assess LRIG3's impact on glioma vascularization in vivo." (PMID 41692232, 2026). "Under hypoxia, LRIG3 overexpression inhibited the invasion and tube formation capacities of glioma cells, whereas its knockdown promoted these activities." (PMID 41692232, 2026). "LRIG3 mRNA expression, in contrast, was significantly higher in grade II gliomas compared to surrounding control tissue, whereas chemotherapy did not significantly affect expression levels in glioblastoma." (PMID 41201961, 2025). "Soluble LRIG3 (sLRIG3) has recently been identified in the cystic fluid of cystic glioma, the serum of glioma patients, and supernatant of glioma cell lines." (PMID 36639372, 2023). "LRIG3 has been identified to negatively regulate multiple tyrosine kinase receptor signaling pathways thus supressing glioma growth." (PMID 36639372, 2023). "To investigate the underlying mechanism, we performed qRT-PCR to quantify levels of mRNAs for angiogenesis-related factors in the glioma cells following LRIG3 knockdown or overexpression." (PMID 33718179, 2021). "In this study, our findings reveal the anti-angiogenic role of LRIG3 and affirm that LRIG3 has a functionally antagonistic relationship with LRIG2 in glioma angiogenesis." (PMID 33718179, 2021). "Collectively, these results suggest that overexpressing LRIG3 suppresses glioma cell-promoted angiogenesis in vitro." (PMID 33718179, 2021). "Taken together, these findings indicate that silencing LRIG3 enhances the pro-angiogenic activity of glioma cells in vitro." (PMID 33718179, 2021). "Western blots corroborated the IHC results, with LRIG3 levels also strongly correlating with those of VEGFA in 10 freshly collected clinical glioma samples." (PMID 33718179, 2021). "Our results suggested that LRIG3 is a potential target for the future development of therapeutic strategies against glioma angiogenesis." (PMID 33718179, 2021). "Based on the results above, it is evident that LRIG3 represents a promising therapeutic target for developing anti-angiogenic strategies against gliomas." (PMID 33718179, 2021). "To ascertain the pathway responsible for LRIG3-mediated VEGFA expression, we used the specific inhibitors of the ERK (PD98059) and AKT (LY292004) pathways to block their activation in glioma cells following LRIG3 knockdown." (PMID 33718179, 2021). "Survival analysis of these patients with glioma indicated that LRIG3 is an important prognostic marker for better survival." (PMID 31245283, 2019). "In the current study, expression levels of LRIG3 in the glioma tissue samples and sLRIG3 in patients' serum and glioma cystic fluid were examined." (PMID 31245283, 2019).
glioma (continued). "Taken together, these results demonstrated that both LRIG3 and sLRIG3 effectively decrease the growth and tumor colony formation of glioma cells in vitro." (PMID 31245283, 2019). "In contrast, several other studies demonstrated that LRIG3 inhibited the proliferation, apoptosis, and invasion of glioma cells by negatively regulating the EGFR signaling pathway." (PMID 31245283, 2019). "Given that sLRIG3 is released from glioma cells overexpressing LRIG3 and can be detected in serum and glioma cystic fluid samples of patients, we further investigated the functions of LRIG3 and sLRIG3 in gliomas." (PMID 31245283, 2019). "To further underscore the functions of LRIG3 on glioma cells, we generated LRIG3-knockdown cell line, A172." (PMID 31245283, 2019). "The specific mechanisms behind LRIG3 ectodomain release from glioma cells and the pattern of the interaction with MET deserve more investigation in the future." (PMID 31245283, 2019). "In this study, we investigated the expression of human leucine-rich repeats and immunoglobulin-like domains protein 3 (LRIG3) in human glioma specimens through immunohistochemical analysis." (PMID 31245283, 2019). "A generally high expression of LRIG3 in patients with grade III gliomas was correlated with good prognosis compared with that in patients with low LRIG3 expression, but the difference was not statistically significant (p = 0.2112)." (PMID 31245283, 2019). "Clinical studies showed that LRIG3 protein expression levels in glioma samples were negatively correlated with WHO grades." (PMID 31245283, 2019). "These assays demonstrated that LRIG3 and sLRIG3 attenuated the migration and invasion of glioma cells." (PMID 31245283, 2019). "Taken together, these results showed that glioma cell lines stably expressing LRIG3 and LRIG3 ectodomain were successfully established and demonstrated the existence of sLRIG3 in the serum and glioma cystic fluid of patients." (PMID 31245283, 2019). "In this study, we demonstrated the existence of soluble ectodomain of the human LRIG3, and reported that LRIG3 and its soluble ectodomain, sLRIG3, inhibited glioma progression through the regulation of the MET/PI3K/Akt pathway both in vitro and in vivo." (PMID 31245283, 2019). "For patients with HGGs, both higher LRIG3 protein expression levels in glioma tissues and higher serum sLRIG3 levels indicated improved prognosis." (PMID 31245283, 2019). "The CCK-8 assay demonstrated that both LRIG3 and sLRIG3 significantly decreased the proliferation rates of glioma cells as compared with that in the control group." (PMID 31245283, 2019). "Further study demonstrated that both LRIG3 and sLRIG3 inhibit the proliferation, migration and invasion of glioma cells by decreasing phosphorylation of MET and downstream signaling components in vitro and in vivo." (PMID 31245283, 2019). "The phenotype of Lrig2E12-/- mice showed that Lrig2 was a promoter of PDGFB-induced glioma, and Lrig2 appeared to have important molecular and developmental functions that were distinct from those of Lrig1 and Lrig3." (PMID 24023893, 2013). "Soluble LRIG3 might regulate the progression of glioma through the interaction between cells in the glioma microenvironment." (PMID 36639372, 2023). "High expression of LRIG3 predicts a good prognosis in patients with glioma." (PMID 36639372, 2023). "Taken together, our results suggest that LRIG3 is a novel regulator of glioma angiogenesis and may be a promising option for developing anti-angiogenic therapy." (PMID 33718179, 2021). "Furthermore, MTT proliferation assay revealed significantly lower cell viability of HUVEC following treatment with CM derived from LRIG3 overexpressed glioma cells." (PMID 33718179, 2021). "Moreover, LRIG3 expression is significantly higher in low-grade gliomas than in high-grade gliomas (grades III and IV), and LRIG3 upregulation suggests a better prognosis in malignant glioma patients." (PMID 33718179, 2021).
glioma (continued). "Previously, we demonstrated that LRIG3 is a critical tumor suppressor in glioma." (PMID 33718179, 2021). "Western blots confirmed altered LRIG3 expression in glioma cells." (PMID 33718179, 2021). "Moreover, western blots and ELISA results indicated that levels VEGFA protein were consistently upregulated and downregulated in LRIG3-knockdown and LRIG3-overexpressing glioma cells, respectively, compared to control cells." (PMID 33718179, 2021). "In summary, we have demonstrated that LRIG3 inhibits angiogenesis in glioma." (PMID 33718179, 2021). "Our previous study demonstrated that LRIG3 could modulate the proliferation, apoptosis, and invasion of glioma cells and functions as a tumor suppressor by attenuating the EGFR signaling pathway." (PMID 31245283, 2019). "Then we constructed glioma cell lines with inducible expression of LRIG3." (PMID 31245283, 2019). "Moreover, we confirmed the existence of soluble ectodomain of LRIG3 (sLRIG3) in the cell culture supernatant, serum, and in tumor cystic fluid of patients with glioma." (PMID 31245283, 2019). "We revealed for the first time a negative association between LRIG3/sLRIG3 and MET signaling in human glioblastoma and provided compelling evidence in support of the hypothesis that LRIG3 and sLRIG3 could serve as tumor suppressors in human gliomas." (PMID 31245283, 2019). "Because of the contradiction in LRIG3 protein function and the fact that the presence and function of soluble LRIG3 (sLRIG3) in gliomas remain unknown, it is essential to further investigate the characteristics of LRIG3 in gliomas." (PMID 31245283, 2019). "Furthermore, we assessed LRIG3 expression levels in 16 fresh frozen glioma tissues (5 grade II, 4 grade III, and 7 glioblastoma samples) and one normal brain tissue via western blotting." (PMID 31245283, 2019). "However, although downregulation of Lrig3 in human glioma cells caused enhanced EGFR levels, more recent studies indicate that Lrig3 actually opposes Lrig1's effects on EGF signaling." (PMID 24086156, 2013). "Furthermore, soft agar colony formation assays showed that significantly fewer and smaller colonies were formed within the experimental groups than those in the control group, indicating that overexpression of LRIG3 and sLRIG3 decreased the anchorage-independent growth of glioma cells." (PMID 31245283, 2019). "Thus, we investigated whether LRIG3 and sLRIG3 could affect the invasion and migration capabilities of glioma cells by performing the wound-healing assay and Matrigel invasion assay." (PMID 31245283, 2019). "Consequently, downregulation of LRIG3 enhanced the proliferation and migration of glioma cells." (PMID 31245283, 2019). "Although our previous study demonstrated that LRIG3 inhibited angiogenesis via the PI3K/AKT/VEGFA pathway under normoxia, its impact on glioma vascularization under hypoxia remains elusive." (PMID 41692232, 2026). "Mechanistically, LRIG3 inhibited activation of the PI3K/AKT signaling pathway, downregulating vascular endothelial growth factor A (VEGFA) in glioma cells, thereby inhibiting angiogenesis." (PMID 33718179, 2021). "In fact, LRIG3 acts as a tumor suppressor in GBM, where it modulates proliferation, migration, and invasion of glioma cells by targeting the EGFR and MET signaling pathways." (PMID 33718179, 2021). "The results showed that LRIG3 was weakly expressed in high-grade gliomas (WHO [World Health Organization] grades III and IV) compared with that in low-grade gliomas (WHO grade II)." (PMID 31245283, 2019). "LRIG3 was, in contrast to LRIG1 and LRIG2, significantly increased in glioma compared to control tissue (1.354 ± 0.89 vs. 0.746 ± 0.242, p = 0.039), with highest difference to grade II glioma (1.556 ± 0.702 vs. 0.746 ± 0.242, p = 0.0.0002)." (PMID 41201961, 2025).
glioma (continued). "Further investigations are still required to identify the specific interactions between LRIG3 protein and the PI3K/AKT signaling pathway, as well as other relevant signaling pathways that might play potential roles in glioma angiogenesis." (PMID 33718179, 2021). "Our recent study indicated that LRIG3 can suppress the growth of GBM cell lines and tumor xenografts in Cell line-derived xenograft model by downregulating the activity of MET/phosphatidylinositol 3-kinase/Akt signaling pathway, thus playing an anti-tumor role in glioma." (PMID 36639372, 2023). "Notably, LRIG3 had a significant negative correlation with VEGFA expression in glioma tissues." (PMID 33718179, 2021).
glioblastoma (5 papers, 2019 to 2026). The most malignant astrocytic tumor (WHO grade IV). "In the present study, we aimed to investigate the existence of sLRIG3 and to further our understanding of the functions of LRIG3 and sLRIG3 in glioblastoma." (PMID 31245283, 2019). "Finally, we validated the association between LRIG3 with p-AKT, and VEGFA in patients using IHC staining of these proteins in 28 glioblastoma specimens." (PMID 33718179, 2021). "Our results suggested that LRIG3 and sLRIG3 may represent novel prognostic markers for patients with glioblastoma or HGG and could be used as potential therapeutic agents in future treatment strategies." (PMID 31245283, 2019). "Taken together, our data for the first time demonstrate the existence of sLRIG3 and that both LRIG3 and sLRIG3 are potent tumor suppressors, which could be used as prognostic markers for better overall survival and therapeutic agents for glioblastoma." (PMID 31245283, 2019). "In summary, LRIG3 and sLRIG3 may represent critical prognostic markers in clinical practice, and sLRIG3 has potential as a therapeutic agent for glioblastoma." (PMID 31245283, 2019). "Since many studies on LRIG gene family members are associated with the regulation of RTKs, it is worthwhile to further elucidate whether LRIG3 regulates the MET signaling pathway in glioblastoma." (PMID 31245283, 2019). "Together, these results affirmed the clinical relevance of the LRIG3/PI3K/AKT/VEGFA axis and confirmed these proteins play a vital role in the regulation of glioblastoma angiogenesis." (PMID 33718179, 2021). "Considering that both LRIG3 in the tumor sample and sLRIG3 in the serum samples are associated with better prognosis of HGG patients, they might represent critical prognostic markers and offer potential in tailoring treatments for patients with glioblastoma in the future." (PMID 31245283, 2019). "Because both LRIG3 and sLRIG3 inhibit the activation and rhHGF-induced activation of the MET signaling pathway, these proteins may be useful in combination with bevacizumab treatment to work alongside conventional anti-glioblastoma therapies to improve patient survival." (PMID 31245283, 2019).
hepatocellular carcinoma (3 papers, 2020 to 2022). A malignant tumor that arises from hepatocytes. "In hepatocellular carcinoma, circ-LRIG3 enhances EZH2 expression and induces STAT3 methylation to promote cancer progression." (PMID 35236381, 2022). "Positive feedback loops between STAT3 and circ-LRIG3 occur through STAT3 binding to promoter of circ-LRIG3 and enhancing STAT3 expression, to subsequently lead to hepatocellular carcinoma progression." (PMID 35236381, 2022). "Circ-LRIG3 interacts with EZH2 and STAT3 to facilitate EZH2-induced STAT3 phosphorylation, resulting in the malignant progression of hepatocellular carcinoma." (PMID 34485151, 2021).
malignant glioma (2 papers, 2019 to 2021). A grade III or grade IV glioma arising from the central nervous system. "In our study, both LRIG3 and sLRIG3 proteins attenuated the progression of malignant glioma through downregulating the activation of MET/PI3K/Akt/mTOR pathway in vitro and in vivo." (PMID 31245283, 2019). "High levels of LRIG3 is associated with the downregulation of EGFR and MET signaling in malignant gliomas, supporting the idea that LRIG3 may be a novel target for anti-angiogenic therapy." (PMID 33718179, 2021).
prostate carcinoma (2 papers, 2021 to 2023). A carcinoma that arises from epithelial cells of the prostate gland. "Two genes, Usb1 and Lrig3, have recently been studied as therapeutic targets in poikiloderma with neutropenia and prostate cancer, respectively, while Ica1 encodes an autoantigen involved in autoimmune insulin-dependent diabetes mellitus and primary Sjogren’s syndrome." (PMID 36818345, 2023).
adenoma (1 paper, 2018). A neoplasm arising from the epithelium. "Meanwhile, the frequency of ERK activity pulses was significantly decreased by the Lrig3 expression (P = 0.0001) and the Troy knockdown (P = 0.0009) in adenoma organoids." (PMID 29872037, 2018). "The knockdown of Egfl6 or expression of Lrig3 abolished the sensitivity of adenoma cells to EGFR inhibition." (PMID 29872037, 2018). "RT-PCR analyses confirmed that Egfl6, Flna, and Troy were upregulated, and that Lrig3 was downregulated in CHIR99021-treated organoids and adenoma-derived organoids." (PMID 29872037, 2018).
Alzheimer disease (1 paper, 2024). A progressive, neurodegenerative disease characterized by loss of function and death of nerve cells in several areas of the brain leading to loss of cognitive function such as memory and language. "Current research has confirmed that downregulating LRIG3 in an Alzheimer’s disease rat model can inhibit oxidative stress damage and inflammatory injury by modulating the PI3/Akt pathway." (PMID 38982427, 2024).